APOM (apolipoprotein M)
Diseases named in the same sentence as APOM in open-access papers (continued):
Sharing a sentence is not in itself a finding about the gene and the disease.
diabetes (continued). "Therefore, the data available from the genetic studies discussed do not indicate that genetic changes in the APOM transcript are associated with an increased risk of diabetes in the general population." (PMID 34093440, 2021). "As a biomarker, apoM may also have the potential to predict the risk of mortality in patients with or without diabetes." (PMID 34093440, 2021). "Several studies reported that apoM plays important roles in diabetes mellitus (DM), endothelial inflammation, and coronary artery disease (CAD)." (PMID 31885732, 2019). "Similarly, plasma apoM is modestly reduced in patients with diabetes compared to controls." (PMID 24642298, 2014). "In addition, plasma apoM is modestly reduced in patients with diabetes compared to controls." (PMID 24642298, 2014). "HDL from humans with type 2 diabetes versus controls has similar ApoM content, but HDL from those with diabetes is less efficient at preventing endothelial TNF-α expression and activating eNOS, functions that correlate with plasma S1P levels." (PMID 35362476, 2022). "Several of the reported proteins, including ApoM, LRG, FBLN3 and PTPRZ, have functions related to cell adhesion, migration, and morphology and have been reported as important in the development of various cancer types as well as diabetes." (PMID 26950848, 2016). "ApoM was not correlated with age, diabetes mellitus(DM) duration, ACR, FPG, HbA1c, CR, SOD, TG, and LP(a) in the four groups." (PMID 27633510, 2016). "ApoM may play an important role in HDL-mediated cholesterol reverse transport and is an attractive target for the treatment of diabetes, obesity, hyperinsulinemia and dyslipidemia." (PMID 26377577, 2015). "Thus, diabetes is today one of the most common diseases leading to CKD, and patients with T2D have decreased apoM levels, which might at least partially explain the low apoM levels seen in patients with CKD." (PMID 34722589, 2021).
type 2 diabetes (25 papers, 2010 to 2026). "For ApoM, human adipose tissue studies reveal reduced ApoM expression in obesity and metabolic syndrome, genetic variants linked to type 2 diabetes, and decreased plasma ApoM in MASLD." (PMID 41303567, 2025). "Since we previously reported an association between APOM gene polymorphism and the disease duration of type 2 diabetes, such association was also tested for the three APOE promoter SNPs." (PMID 22028770, 2011). "This study aimed at substantiating the associations of the apolipoproein M gene (APOM) with type 2 diabetes (T2D) as well as with metabolic traits in Hong Kong Chinese." (PMID 21390319, 2011). "APOM, known for cholesterol regulation, confers risk for the development of type 2 diabetes through SNP T-778C in the proximal promoter region among Han Chinese." (PMID 20806066, 2010). "Clinical and preclinical studies have linked reduced ApoM expression with cardiometabolic diseases, such as obesity, insulin resistance, type 2 diabetes, and chronic kidney disease, while emerging evidence also implicates ApoM in neurovascular, inflammatory, and retinal disorders." (PMID 41771322, 2026). "In addition, several genetic variants of the APOM gene identified in the Chinese population have been associated with reduced plasma ApoM concentrations and an increased risk of developing type 2 diabetes." (PMID 41303567, 2025). "Moreover, total plasma S1P and ApoM levels are inversely associated with mortality in type 2 diabetes." (PMID 35104242, 2022). "Moreover, some genetic variants of the APOM gene reported in the Chinese population associate low plasma APOM levels with a higher risk of developing type 2 diabetes." (PMID 34638803, 2021). "Several additional lines of evidence also indicated the possible involvement of APOM in the development of diabetes and metabolic disturbances: 1) the human APOM gene is located within a high susceptibility region (6q21–q23) to type 2 diabetes (T2D) in genome-wide linkage analyses." (PMID 21390319, 2011). "In this context, circulating apoM, the main carrier of S1P in HDL, is reduced in patients with type 2 diabetes as a result of the impact of insulin resistance on the production of ApoM." (PMID 39984928, 2025). "Participants with type 2 diabetes had lower circulating adiponectin and apoM, while apoM was higher in individuals with dyslipidemia." (PMID 38491190, 2024). "This review discusses the specific elements indicative of the protective or harmful effects of apoM, S1P, and the apoM/S1P complex on type 2 diabetes development." (PMID 34093440, 2021). "Single nucleotide polymorphism (SNP) T-778C, C-724del and T-855C in the proximal promoter region of apoM gene have significant associations with CAD and type-2 diabetes among Han Chinese." (PMID 26377577, 2015). "ApoM, which is mainly associated with HDL, is reduced in patients with type 2 diabetes due to diabetes-associated obesity." (PMID 25725623, 2015). "Clinical studies show that serum apolipoprotein M (ApoM) levels in patients with type 2 diabetes inversely correlate with the progression of diabetic nephropathy, suggesting that ApoM/S1P could help in preventing and mitigating diabetic nephropathy." (PMID 39777222, 2024). "Studies in humans have shown that total plasma ApoM levels are reduced in type 2 diabetes." (PMID 35104242, 2022). "In controls and individuals with type 2 diabetes, plasma ApoM levels predict pre–β-HDL levels." (PMID 35362476, 2022). "Plasma levels of apoM were also decreased in maturity-onset diabetes of the young (MODY3) subjects, might attribute to the hepatocyte nuclear factor-1α (HNF-1α)-dependent impairment of apoM expression leaded by heterozygous HNF-1α mutations." (PMID 27576735, 2016). "The decreased serum apoM level in maturity-onset diabetes of the young subjects as compared to the controls could be explained by the HNF-1 alpha mutations in these patients." (PMID 21390319, 2011).
type 2 diabetes (continued). "Moreover, apoM over expression might have a potential role in improving insulin resistance, further explain that modulating apoM expression might against insulin resistance in type 2 diabetes." (PMID 27576735, 2016). "Therefore, modulating ApoM expression might be a future therapeutic strategy against insulin resistance in type 2 diabetes." (PMID 25144649, 2014). "ApoM overexpression may have a potential role in improving insulin resistance in vivo and modulating apoM expression might be a future therapeutic strategy against insulin resistance in type 2 diabetes." (PMID 25144649, 2014). "Our results suggest that ApoM overexpression may have a potential role in improving insulin resistance in vivo, and could be considered as a future therapeutic target against insulin resistance and type 2 diabetes." (PMID 25144649, 2014). "Other studies demonstrated that circulating ApoM levels are significantly lower in individuals with obesity, metabolic syndrome, type 2 diabetes and gestational diabetes compared to lean, non-diabetic controls." (PMID 41303567, 2025). "Moreover, the present study may open a new sight into the pathophysiological procedure of the apoM and apoM overexpression for a potential role on improving lipoprotein metabolism in vivo, which could be considered as a future therapeutic target against insulin resistance and type-2 diabetes." (PMID 26377577, 2015). "ApoM promotes the formation of pre–β-HDL from α-HDL, and lower levels of ApoM may explain why pre-β-HDL formation is not increased in type 2 diabetes, despite increased PLTP activity." (PMID 25725623, 2015).
Insulin resistance (22 papers, 2014 to 2026). Increased resistance towards insulin, that is, diminished effectiveness of insulin in reducing blood glucose levels. "A study recently proposed that apoM/S1P association protected against the development of glucose intolerance and insulin resistance in HFD fed mice." (PMID 37628901, 2023). "In addition, insulin secretion during intraperitoneal glucose tolerance tests was attenuated in apoM-KO mice, indicating that apoM deficiency exacerbated insulin resistance during HFD." (PMID 37628901, 2023). "We hypothesized that downregulation of ApoM expression by hyperglycemia may be associated with insulin resistance." (PMID 25144649, 2014). "Insulin resistance is associated with decreased ApoM levels." (PMID 25144649, 2014). "However, serum apoM levels were inversely associated with BMI and the insulin resistance index." (PMID 38256005, 2024). "Finally, insulin resistance is associated with a decrease in plasma apoM." (PMID 36335116, 2022). "Gene expression of APOM in AT is lower in individuals with high body fat, metabolic syndrome, or insulin resistance (IR) compared to lean healthy individuals." (PMID 38491190, 2024). "Deterioration of insulin resistance was observed in apoM−/− mice, and improved insulin resistance was observed in apoM-overexpressing mice." (PMID 38256005, 2024). "ApoM−/− mice exhibited deteriorated insulin resistance, whereas apoM-overexpressing mice showed improvements in insulin resistance, presumably through the activation of S1P1/3 signaling." (PMID 38256005, 2024). "Treatment with S1P1 and S1P3 antagonists partially reversed the beneficial effects of apoM overexpression on fasting blood glucose levels and insulin resistance." (PMID 37628901, 2023). "In contrast, ApoM was shown to promote insulin secretion and antagonize insulin resistance after activating S1PR1 and/or S1PR3 signaling." (PMID 37867511, 2023). "Insulin resistance itself led to a reduction in the production of apoM and a decrease in S1P/HDL levels." (PMID 37628901, 2023). "Altogether, these studies demonstrated that the regulation of apoM/S1P levels is central for the development of glucose intolerance and insulin resistance in diabetes." (PMID 37628901, 2023). "We investigated ApoM expression and S1P distribution in mouse models of hyperinsulinemia and insulin resistance." (PMID 35104242, 2022). "In a model of polymicrobial sepsis, berberine removed damaged GVB resulting from TLR4-mediated hyperglycemia, insulin resistance and proinflammatory molecule production, thus enriching ApoM gene expression and plasma ApoM via activating the ApoM/S1P pathway." (PMID 35370628, 2021). "Apolipoprotein M (apoM) is a multifunctional lipid mediator on HDL that was observed to be negatively correlated with BMI and the insulin resistance index, suggesting that apoM exerts protective roles against the development of insulin resistance." (PMID 34957229, 2021). "We examined the effect of glucosamine, a prominent component of hexosamine pathway and intracellular mediator of insulin resistance, on apoM expression in HepG2 cells and in rat’s models." (PMID 26377577, 2015). "In mice, APOM inhibits lipid uptake by adipocytes and promotes insulin resistance." (PMID 39498350, 2024). "In mice, the absence of the S1P vector (Apolipoprotein M, ApoM) was associated with worsening insulin resistance." (PMID 37867511, 2023). "Similarly, serum ApoM levels were lower in T2 DM patients and negatively correlated with insulin resistance." (PMID 37867511, 2023). "In addition, TLR4 can mediate hyperglycemia, insulin resistance and proinflammatory molecule production, decreasing ApoM gene expression and plasma ApoM, damage gut-vascular barrier (GVB), thereby aggravate the intestinal function." (PMID 36088483, 2022).
Insulin resistance (continued). "For the four proteins that differed between PCOS subjects and control women (ApoE, ApoM, C3, and HCFII), correlations with age; BMI; insulin resistance (HOMA-IR); testosterone; and circulating levels of TG, cholesterol, HDL-C, LDL-C, and CRP were performed." (PMID 36980195, 2023). "A second study also supported these observations, and showed that ApoM-KO mice fed HFD were glucose intolerant and exhibited worsening insulin resistance, whereas mice with apoM overexpression showed improvement of insulin resistance." (PMID 34093440, 2021). "It appeared that the increased intracellular content of glucosamine, a known mediator of insulin resistance, not be responsible for the reduced apoM expression in hyperglycemia condition." (PMID 26377577, 2015). "We investigated the effects of overexpressing the human ApoM gene on insulin sensitivity in GK rats, which is a non-obese Wistar substrain rat characterized by mild hyperglycemia, insulin resistance and hyperinsulinemia." (PMID 25144649, 2014). "However, the distribution of ApoM and S1P on fractionated lipoproteins has not, to our knowledge, been studied in mouse models of insulin resistance." (PMID 35104242, 2022). "It has been suggested that the ApoM/S1 complex has a protective role against the development of insulin resistance, a common feature of PCOS; therefore, lower ApoM levels may contribute to the insulin resistance commonly seen in PCOS and that is an independent cardiovascular risk marker." (PMID 36980195, 2023). "Altogether, these data suggest that ApoM expression and S1P binding to HDL are affected in some, but not all, models of obesity, hyperinsulinemia, and insulin resistance." (PMID 35104242, 2022).
Sepsis (22 papers, 2012 to 2025). Sepsis is defined as life-threatening organ dysfunction caused by a dysregulated host response to infection. "Our findings have multiple translational implications and link SGLT2i to the ApoM/S1P pathway, which is inversely associated with mortality in COVID-19,27,47 sepsis, HF 25, and T2DM." (PMID 40579057, 2025). "Gel filtration chromatography of plasma from severe human or baboon sepsis on Superose 6 demonstrated an almost complete loss of S1P and apoM in the HDL fractions." (PMID 26990127, 2016). "This study aims at elucidating the response of the endothelial‐protective S1P and its carrier protein apoM to the inflammatory challenge associated with sepsis and SIRS." (PMID 26990127, 2016). "Increased vascular leakage is a hallmark of sepsis, and it is likely that the decrease in S1P-associated apoM would contribute to this." (PMID 22512779, 2012). "The drastic decrease in apoM plasma concentrations caused by the severe acute-phase response of sepsis presumably results in decreased S1P concentrations and, as a consequence, decreased barrier function." (PMID 22512779, 2012). "Interestingly, in the plasma from severe sepsis subjects, an almost complete loss of S1P and ApoM was demonstrated in the high-density lipoprotein fractions." (PMID 37685894, 2023). "Furthermore, berberine can also induce Zrt-Irt-like protein 14 expression to protect the intestinal barrier in sepsis, and ameliorates sepsis-induced reduction in intestinal vascular barrier permeability caused by sepsis by modulating the ApoM/S1P pathway." (PMID 36188532, 2022). "Reduction in apoM’s availability to bind to circulating S1P causes endothelium dysfunction, chronic inflammation, and diseases ranging from cardiovascular diseases, cancer, and infections such as sepsis." (PMID 35158806, 2022). "In a study on sepsis and systemic inflammatory response syndrome (SIRS), the plasma concentration of apolipoprotein M (apoM) was decreased in patients with sepsis and SIRS than in controls." (PMID 38482014, 2024). "ApoM is required for HDL biogenesis and 95% of plasma ApoM is found associated with HDL, both are significantly reduced during sepsis." (PMID 36915826, 2023). "In agreement with the ApoM-S1P proposed effects, it has been observed that, in human sepsis, the disease severity was correlated with decreased S1P levels, a profile mimicking that of plasma ApoM." (PMID 37685894, 2023). "Similar to the human sepsis cohort, where the S1P and apoM levels decreased in relation to the severity of disease, baboons with the most severe disease had the most pronounced decrease in S1P and apoM." (PMID 26990127, 2016). "The liver mRNA levels of apoM and apoA1 decreased strongly upon sepsis induction and after 12 hr both were almost completely lost." (PMID 26990127, 2016). "To study S1P and apoM in further detail, we used a well‐characterized baboon model of sepsis where the disease progression is similar to that of human sepsis." (PMID 26990127, 2016). "In the lethal E. coli baboon sepsis, S1P decreased already within 6–8 hrs, whereas the apoM decrease was seen later at 12–24 hrs." (PMID 26990127, 2016). "Upon sepsis induction in both the LD50 and LD100 groups, the apoM‐associated S1P peak decreased, being too low to be measurable in the LD100‐group." (PMID 26990127, 2016). "In a human sepsis cohort, previously studied for apoM, we found disease‐severity correlated decrease in plasma S1P levels, the profile mimicking that of plasma apoM." (PMID 26990127, 2016). "There was a weak but significant correlation between plasma levels of apoM and S1P in the sepsis patients (rS = 0.22, P = 0.0021)." (PMID 26990127, 2016). "ApoM gene expression is decreased in systemic inflammation stimulated by lipopolysaccharides (LPS), zymosan, or turpentine, as well as in patients with sepsis." (PMID 27001252, 2016).